DQX1 (DEAQ-box RNA dependent ATPase 1)
Description:
Might be involved in RNA metabolism; it is missing helicase motif III and may not have helicase activity.
Synonyms: FLJ23757
Tractability: No criterion of Open Targets' tractability assessment is met for any kind of drug.
Gene: Protein-coding gene on chromosome 2 (74,518,131 to 74,526,396, reverse strand). Ensembl gene ENSG00000144045.
Subcellular location: Nucleus
Subcellular location (Human Protein Atlas): Nucleoli fibrillar center
Gene Ontology:
Molecular function: helicase activity
Cellular component: spliceosomal complex; nucleus
Genetic constraint (gnomAD): Loss-of-function variants: 66 observed, 83.43 expected, observed/expected ratio (o/e) 0.79, 90% interval 0.65 to 0.97. The synonymous counts are far from expectation, so gnomAD's model fits this gene poorly and the ratio says little. Missense variants: 798 observed, 905.3 expected, observed/expected ratio (o/e) 0.88, 90% interval 0.83 to 0.94. Synonymous variants: 290 observed, 367.36 expected, observed/expected ratio (o/e) 0.79, 90% interval 0.72 to 0.87.
Homologues: Orthologues: chimpanzee DQX1 (99% identical), macaque DQX1 (97% identical), pig DQX1 (90% identical), dog DQX1 (88% identical), guinea pig DQX1 (87% identical), mouse Dqx1 (84% identical), rat Dqx1 (84% identical), rabbit DQX1 (83% identical), tropical clawed frog dqx1 (53% identical), zebrafish dqx1 (34% identical). Paralogues in human: DHX32 (44% identical), DHX15 (36% identical), DHX35 (30% identical), DHX8 (30% identical), DHX16 (30% identical), DHX38 (29% identical), DHX34 (28% identical), DHX40 (25% identical), DHX33 (25% identical), DHX37 (24% identical), DHX29 (24% identical), DHX57 (23% identical), and 6 more.
Diseases named in the same sentence as DQX1 in open-access papers:
DQX1 is named in the same sentence as 6 diseases in open-access papers, as found by Europe PMC text mining. Sharing a sentence is not in itself a finding about the gene and the disease. The quoted sentences say what the papers report.
liver cancer (1 paper, 2024). An epithelial or non-epithelial malignant neoplasm that arises from the liver. "Gene set enrichment analysis (GSEA) is further performed to explore the signaling pathways and molecular mechanisms that were differentially affected by DQX1 in liver cancer." (PMID 38463168, 2024). "In this study, we focus on the analysis of the relationship between DQX1 expression and survival in liver cancer." (PMID 38463168, 2024). "This suggests that we can develop immunotherapies targeting DQX1 for the treatment of liver cancer, in the future." (PMID 38463168, 2024). "TIMER, a comprehensive online resource for the systematic analysis of immune infiltrates in various cancer types, is employed in this study to explore the correlation between DQX1 expression in liver cancer and different immune infiltrates." (PMID 38463168, 2024). "Our analysis has identified three potential oncogenes, ARHGEF39, UBE2C, and DQX1 of liver cancer." (PMID 38463168, 2024). "Based on the bioinformatics analysis, we have been inferred that DQX1 may potentially act as an oncogene and be involved in the development of liver cancer." (PMID 38463168, 2024). "The results indicate that DQX1 may be a potential oncogene in liver cancer and may contribute to tumor immune escape." (PMID 38463168, 2024). "Integrative analysis of gene expression differences in liver cancer further highlights three genes: ARHGEF39, UBE2C and DQX1." (PMID 38463168, 2024). "However, there is currently no literature exploring the role of the DQX1 in liver cancer." (PMID 38463168, 2024).
pancreatic cancer (1 paper, 2020). "However, there were also proteins that, to the best of our knowledge, have not yet been associated with oncogenic potential in pancreatic cancer, e.g., OAS proteins, RBM34 or DQX1." (PMID 32545414, 2020).
renal cell carcinoma (1 paper, 2022). "Furthermore, DQX1 is reportedly associated with the prognosis of renal cell carcinoma." (PMID 36147491, 2022).
tumor (1 paper, 2024). "And overexpression of DQX1 is associated with poor prognosis and tumor immune escape." (PMID 38463168, 2024). "In this study, the tumor samples are grouped based on the mean expression level of DQX1." (PMID 38463168, 2024).
DQX1 also shares sentences with these, for which no sentence is quoted: cancer (1 paper); lung squamous cell carcinoma (1).